IL6 (interleukin 6)
Diseases named in the same sentence as IL6 in open-access papers (continued):
Sharing a sentence is not in itself a finding about the gene and the disease.
psoriasis (continued). "This may reinforce the interest about IL-6 in the early phase of psoriasis supporting the role as candidate diagnostic molecule in new-onset psoriasis." (PMID 34006909, 2021). "Increased levels of pro-inflammatory cytokines, especially IL-6, in patients with psoriasis may be one of the causes of the decline in adiponectin levels in subcutaneous and visceral adipose tissue." (PMID 34372872, 2021). "Any perturbation of the balance between the pro- and anti-inflammatory signals (such as the loss of IL-6) may lead to the development of chronic inflammatory conditions such as psoriasis or atopic dermatitis." (PMID 34295313, 2021). "In psoriasis, IL-6 has been long associated with disease pathogenesis." (PMID 34215755, 2021). "Finally, we did not measure and adjust for inflammatory markers, such as C-reactive protein and IL-6, which were supposed to be associated with sarcopenia and psoriasis." (PMID 34722590, 2021). "STAT3 participates in signaling downstream of multiple cytokines implicated in psoriasis, such as IL-6, IL-10, IL-20, IL-22, and IL-23, and may have a role in mediating the innate immune response in psoriatic epidermis." (PMID 32752186, 2020). "Interestingly, psoriasis-associated cytokines especially IL-17A and IL-6, can directly positively regulate keratinocytes to over-express OAS2." (PMID 32849499, 2020). "Indeed, mice with PD-1-deficiency specifically in CD8 T cells display severe psoriasis-like dermatitis, which can be restrained by blockade of IL-6 signaling." (PMID 33060784, 2020). "Any factor that raises the level of IL-6 could be a risk factor in stimulating the pathogenesis of psoriasis." (PMID 31291937, 2019). "Notably, genetic polymorphisms in IL-6 are associated with the risk of psoriasis." (PMID 40898481, 2025). "The release of IL-6 is one of the key inflammatory signals causing activation of matrix metalloproteinases, macrophages, neutrophil production, and is also involved in autoimmune responses in the condition such as chronic arthritis, osteoporosis, and psoriasis." (PMID 31906495, 2020). "Increased levels of TNF-α and IL-6 before the onset of infection are associated with an increased risk of pneumonia requiring hospitalization, suggesting that overproduction of these cytokines can trigger bacterial invasion and the development of pneumonia in patients with psoriasis." (PMID 32987907, 2020). "Although let-7b was reported to modulate inflammatory cytokines such as IL-6 in cholangiocarcinoma by short-term oxidative stress responses, the in vivo function of let-7b and the underlying mechanisms by which let-7b regulates cell differentiation in psoriasis is poorly understood." (PMID 30219085, 2018). "Probiotics are associated with significantly reduced Psoriasis Area and Severity Index (PASI) scores, increased PASI 75 response rates, lowered inflammatory biomarkers (CRP, TNFα, IL-6) and improved Dermatology Life Quality Index (DLQI)." (PMID 42005309, 2026). "Across all conditions, migration of inserted T cells towards the epidermis and the secretion of psoriasis-associated cytokines (IFN-γ, IL-17, TNF-α, IL-1β, CCL20, IL-6, and IL-10) was observed." (PMID 42039187, 2026). "As a main originator of inflammatory signaling, TNF-α triggers a cascade that includes IL-6 and other cytokines, particularly in acute and chronic inflammatory disorders such as inflammatory bowel disease and psoriasis." (PMID 39755644, 2025). "IL‐6 is involved in the activation and recruitment of immune cells, contributing to chronic inflammation in conditions like psoriasis and atopic dermatitis." (PMID 40414816, 2025). "Another study on IL-6 states that serum IL-6 levels are considered a marker of inflammatory activity in psoriasis and a useful indicator of treatment response." (PMID 40733073, 2025).
psoriasis (continued). "Dendritic cells and macrophages in the dermis of psoriasis produce IL-23, which induces the activation of Th17 cells and γδ T cells and the release of inflammatory cytokines, such as IL-17A, IL-17F, IL-22, IL-6 and tumor necrosis factor-α (TNF-α)." (PMID 40303403, 2025). "Psoriasis patients displayed significantly higher IL-6 than controls (38.1 pg/mL [35.5–41.3] vs. 21.4 pg/mL [19.5–33.4]; p<0.001)." (PMID 41472738, 2025). "In patients with psoriasis, serum IL-6 levels ranged from 7 to 183 pg/mL, with a mean of 61.26 ± 57.40 pg/mL." (PMID 40733073, 2025). "Although reported results vary, it is generally assumed that serum levels of proinflammatory cytokines, such as TNF-α, IFN-γ, IL-6, IL-8, IL-12, IL-17A, IL-18 and IL-22, are elevated in patients with psoriasis and correlate with disease severity." (PMID 40584532, 2025). "In psoriasis, IL-6 is produced by keratinocytes, fibroblasts, endothelial cells, dendritic cells (DCs), macrophages, and T helper 17 cells." (PMID 40906403, 2025). "HCV induces the production of inflammatory cytokines such as cathelicidin, TLR9, IFNγ, TNF-α, and IL-6, all of which are key contributors to psoriasis pathogenesis." (PMID 40724556, 2025). "Their gene expression analysis revealed that IL-6 expression was significantly elevated in PsA (192-fold) and psoriasis (147-fold) patients compared to healthy controls." (PMID 40343299, 2025). "Treatments involving Treg‐of‐B cells activate M2 macrophages via the STAT6 pathway, reducing TNF‐α and IL‐6 production and alleviating psoriasis symptoms in mice." (PMID 40539722, 2025). "In this study, we show that IL-6 remains elevated in patients with psoriasis despite achieving near-complete skin clearance, independent of treatment modality (topical agents, methotrexate, or biologics)." (PMID 41472738, 2025). "The pro-inflammatory cytokines interleukin 23 (IL-23), IL-6, IL-1, and TNF-α are associated with the pathophysiology of psoriasis." (PMID 38712377, 2025). "Increased levels of IL-6, PAI-1, and TNF-α, commonly associated with visceral obesity, have also been found in psoriasis." (PMID 40909067, 2025). "Adipose tissue has been identified not only as an active endocrine organ, but also an immune organ that produces varied immune cells and inflammatory-related cytokines such as TNF-α, leptin, and IL-6, which exacerbate the inflammatory processes in psoriasis." (PMID 40796893, 2025). "A significant correlation between elevated serum levels of TNF-α, IL-6 and IL-17 with psoriasis severity." (PMID 41393395, 2025). "While classical biomarkers such as CRP and IL-6 are widely used in psoriasis-related research and clinical monitoring, each has limitations." (PMID 40722707, 2025). "This substantial difference was found to be highly statistically significant (p < 0.001), underscoring TNF-α and IL-6′s role as key pro-inflammatory cytokines in the pathogenesis of psoriasis." (PMID 40733073, 2025). "Previous studies have suggested a potential role of FOXP3+ in the pathogenesis of psoriasis through the IL-6 and TGF-β pathways." (PMID 40584971, 2025). "The results demonstrated elevated levels of IL-4 and IL-6 in psoriasis-induced samples compared to control, indicating heightened inflammatory responses." (PMID 40818978, 2025). "The ELISA results in our study support these findings, showing that MSC treatment significantly reduced IL-6 and IL-4 levels compared to the psoriasis-induced group." (PMID 40818978, 2025). "In patients with psoriasis, elevated IL-6 concentrations have been correlated with the severity of cutaneous and joint involvement, as IL-6 plays a key role in sustaining inflammation and promoting synovial hyperplasia." (PMID 40731810, 2025). "These cytokines also induce IL-6, leading to the increased proliferation of keratinocytes in psoriasis patients." (PMID 40004904, 2025).
psoriasis (continued). "Here, docetaxel (DTX)-loaded liposomes-in-gel (DTX-LP-G) as the transdermal delivery was investigated to the treatment of psoriasis via modulating the IL6-HIF-1α-VEGF axis." (PMID 40277665, 2025). "Recent studies have found that IL-6 drives psoriasis inflammation and abnormal proliferation of KCs through multiple signaling pathways." (PMID 40898481, 2025). "We thus blocked the proinflammatory cytokines TNF-α, IL-6, IL-1β, and IL-23A, which are known to be crucial to γδ T cell activation, in WT and Acvr1b-Lyz2cre mice during psoriasis." (PMID 40067393, 2025). "Studies have demonstrated that patients with active psoriasisexhibit elevated TNF-α, IL-6 and IL-17 levels, which positively correlate with Psoriasis Area and Severity Index (PASI) scores." (PMID 41393395, 2025). "The elevated levels of IL-6 and IL-18 also correlate with inflammatory responses, as observed in the control psoriasis group in the referenced meta-analysis." (PMID 40678000, 2025). "Several parameters pivotal inflammatory factors in psoriasis have been observed in this study, including IL-6, IL-17, TNF-α, and VEGF." (PMID 38712377, 2025). "To further explore the inflammatory cytokines regulated by TP treatment, we extracted serum from the mice and analyzed the expression of inflammatory genes, such as IL-17A, IL-22, IL-23, TNF-α, and IL-6, which were closely related to psoriasis pathogenesis." (PMID 40365308, 2025). "In this study, we measured serum IL-6 in well-treated psoriasis patients and healthy controls, examining its relationship with key psoriatic cytokines and visceral adiposity assessed by VAI." (PMID 41472738, 2025). "Increased levels of IL-6 were observed, not only in psoriatic lesions and keratinocytes, but also in the plasma/serum of patients with psoriasis, compared to the levels of IL-6 in healthy individuals." (PMID 39858442, 2025). "KD reduces inflammatory cytokines, such as IL-6, IL-17, and IL-23, which have a significant role in the etiopathogenesis of psoriasis." (PMID 41178942, 2025). "A previous report showed that TNF-α and IL-6 levels are higher in psoriasis patients compared to healthy individuals." (PMID 40733073, 2025). "DCs in the skin release proinflammatory cytokines such as tumor necrosis factor-alpha (TNF-α), interleukin 23 (IL-23), IL-6, and IL-1b as psoriasis spreads." (PMID 38712377, 2025). "As we can see, additional preconditioning of hUCB-MSCs with proinflammatory cytokines (IL-17, IL-22, and TNF-α), which are elevated in patients with psoriasis, promotes higher expression of IL-6 protein." (PMID 40906403, 2025). "IL-6 is pivotal in developing and exacerbating skin troubles, including acne, psoriasis, and atopic dermatitis." (PMID 40227405, 2025). "Psoriasis is associated with systemic inflammation characterized by elevated levels of pro-inflammatory cytokines such as TNF-α and IL-6, which not only contribute to skin pathology, but also interfere with metabolic processes." (PMID 40277935, 2025). "The consistent pattern of increased TNF-α, IL-6 and IL-17 levels supports the paradigm shift from viewing psoriasis as apurely cutaneous disease to recognizing it as a systemic immune-mediated disorder." (PMID 41393395, 2025). "HaCaT cells were subjected to treatment with interleukin-6 (IL-6) to create a psoriasis-like cellular model." (PMID 40756706, 2025). "The therapeutic effect of Astragalus (mainly cycloastragenol) in patients with psoriasis is attributable to reduced production of pro-inflammatory interleukins (IL-β1, IL-6, and IL-12)." (PMID 40284164, 2025). "Overall, IL-6 levels in treated psoriasis patients seem to be predominantly influenced by residual pro-inflammatory activity." (PMID 41472738, 2025). "Recent evidence has also reported significant increases in IL-6 and IL-1β across different severities of psoriasis, as measured by PASI and BSA scores." (PMID 40004904, 2025).
psoriasis (continued). "It is also shown that IL-6 affects the hyperproliferation of epidermal cells that is characteristic for psoriasis." (PMID 39858442, 2025). "Pre-stimulation with IL-17 or IFN-γ, cytokines involved in the pathogenesis of psoriasis, further enhanced R7-induced IL-6 secretion." (PMID 40461723, 2025). "Previously, the expression of the IL-6 gene was considered a marker of the pathological state of psoriasis and psoriatic arthritis." (PMID 40343299, 2025). "The therapeutic effect of cycloastragenol in patients with psoriasis can be attributed to its ability to reduce the production of pro-inflammatory interleukins (IL-β1, IL-6, and IL-12)." (PMID 40284164, 2025). "Psoriasis-like mice was induced by imiquimod (IMQ) inducing BALb/c mice, and psoriasis-like keratinocytes was constructed by IL-6 stimulation in HaCaT cells." (PMID 40756706, 2025). "In psoriasis, resistin is involved in the disease’s progression and development via the release of pro-inflammatory cytokines including IL-6, IL-2, and TNF-α." (PMID 40724556, 2025). "Numerous studies have demonstrated that the serum levels of TNF-α, IFN-γ, IL-6, IL-8, IL-12, IL-18, and IL-30 are significantly elevated in patients with active psoriasis compared to healthy individuals." (PMID 40731810, 2025). "This is similar to the results of our study, where we confirmed the existence of elevated levels of pro-inflammatory cytokines in patients with moderately severe and severe psoriasis, especially of IL-6." (PMID 39858442, 2025). "In vitro experiments confirmed that MDMs derived from psoriasis patients overexpressed pyroptosis-related molecules (Caspase 1 and Caspase 4) as well as pro-inflammatory cytokines (TNFα, IL6, IL1β) when compared to healthy controls." (PMID 40722833, 2025). "Next, we addressed the influence of the disease-specific cytokines of psoriasis (Th1, Th17) or AD (Th2) on the R7-triggered release of IL-6." (PMID 40461723, 2025). "Results showed that IFN-γ, TNF-α, IL-1β, IL-6, IL-17A, IL-18, and IL-23 in psoriasis patients had significantly higher levels compared to controls and a strong correlation between PASI scores and these cytokines." (PMID 40699767, 2025). "This study explores regenerative therapies—exosomes, mesenchymal stem cells (MSCs), epigallocatechin-3-gallate nanoparticles (EGN), and EGN-loaded exosomes (EGN-Exo)—in regulating psoriasis-related markers (IL-6, IL-4, Bcl-2, Bax, NF-κB, CDC25B)." (PMID 40818978, 2025). "Th1 and Th17 cells play a key pathogenic role in psoriasis through the release of several cytokines including tumor necrosis factor alpha (TNF-α), and IL-17A, which, in turn, trigger the release of IL-6 and IL-1α by keratinocytes." (PMID 40046180, 2025). "Overactivation of Treg/Th17 cells accelerates psoriasis progression by releasing various inflammatory factors, such as IL-23, IL-17A, IL-22, IL-6, and IFN-α." (PMID 41425939, 2025). "The levels of markers associated with inflammation, namely IL-8, IL-6, CXCL10, and COX-2, were decreased in a psoriasis-like 3D reconstructed skin model by the effect of exosomes from mononuclear cells of human umbilical cord blood (UCB-MNC-sEV)." (PMID 40906403, 2025). "Inflammatory factors in psoriasis patients, such as TNF-α, IL-6, IL-22, etc., in addition to causing skin lesions, also promote the occurrence of metabolic disorders and increase the risk of MetS." (PMID 40385577, 2025). "Several interleukins including IL-17A, IL-22, IL-23, IL-36γ, IL-6, and IL-1β have emerged as the potential biomarkers of subclinical inflammation and treatment resistance in psoriasis." (PMID 40731810, 2025). "Interestingly, in HLA-Cw6+ patients experiencing guttate psoriasis flare-ups associated with pharyngitis, the Th17-associated response is more pronounced, leading to significantly elevated levels of IL-17A, IL-17F, and IL-6, which are involved in Th17 differentiation." (PMID 40303401, 2025).
psoriasis (continued). "IL-6 levels were significantly higher in psoriasis patients compared to healthy controls (median 38.1 vs. 21.4; p < 0.001)." (PMID 41472738, 2025). "This inhibition resulted in a significant decrease in key inflammatory cytokines (Il1b, Il6, Il12b, Il17a, Il22, and Tnf) that are critical in psoriasis’ pathogenesis." (PMID 39335596, 2024). "In psoriasis, proinflammatory cytokines, like interleukin-6 (IL-6), TNF-a, and interleukin-1 beta (IL-1β), play a pivotal role in driving the chronic inflammation observed in skin lesions." (PMID 38337350, 2024). "The present study concludes that there are variations in the lipid profile and increased IL-6 activity in patients with PsA compared to those with psoriasis." (PMID 39429270, 2024). "The correlation among IL-6, lipid profile, and psoriasis area severity index (PASI) score was analyzed using Pearson’s correlation coefficient." (PMID 39429270, 2024). "To summarize our results, we showed that incubation of full-thickness skin models with cytokines leads to a psoriasis-like phenotype with reduced epidermis thickness, parakeratosis, and IL-6 induction." (PMID 37707681, 2024). "At the end of psoriasis (Day 7), IL-6 expression increased with the Sialostatin L treatment, while Sialostatin L2, Iristatin, and Mialostatin significantly decreased its expression." (PMID 38444844, 2024). "The activated JAK-STAT signaling pathway up-regulates the expression of ILs, such as IL-6, IL-17, IL-22, and INF-c, thus causing skin diseases, such as atopic dermatitis and psoriasis." (PMID 38731895, 2024). "In particular, pro-inflammatory cytokines, including interleukin-6, play a significant role in the pathogenesis of both psoriasis and KS." (PMID 39337120, 2024). "Adipose tissue acts as an endocrine organ, resulting in the formation of cytokines associated with both psoriasis and NAFLD (adipocytokines, adipokines (leptin and resistin) TNF-α, and IL-6)." (PMID 38473907, 2024). "The systemic inflammation linked to psoriasis, characterized by elevated cytokines such as TNF-α, IL-6, and IL-17, raises the likelihood of metabolic imbalances." (PMID 39767248, 2024). "Given that both TNF-α and IL-6 are known to contribute to the onset and progression of NAFLD, the cause of this is most likely the elevated levels of both cytokines in psoriasis." (PMID 38707119, 2024). "They further demonstrated the potential efficacy of IL-6–targeting therapy for anti-PD-1/PD-L1-induced psoriasis." (PMID 38347543, 2024). "Except for Iristatin, all the other tested cystatins increased the expression of IL-6 at the peak of psoriasis (Day 4)." (PMID 38444844, 2024). "Nevertheless, the results suggest that basally applied C3bot had only minor effects on the psoriasis-like phenotype despite inhibition of RhoA and reduction of IL-6 abundance in induced psoriasis." (PMID 37707681, 2024). "Herein, we demonstrate that ursolic acid displays the potential to decrease HaCaT-mediated IL-6 production in vitro in a highly psoriasis-stimulating environment." (PMID 38672088, 2024). "The analysis demonstrated that schizandrin II directly influenced psoriasis-related proteins such as IL-4, IL-6, STAT3, and NFKBIA, while schizandrin A modulated the NFKBIA protein." (PMID 39590306, 2024). "The levels of pro-inflammatory cytokines such as tumor necrosis factor-α, interleukin 1β, and interleukin 6 are elevated in psoriasis and participate in the activation of the lectin-like oxidized low-density lipoprotein receptor-1." (PMID 39085887, 2024). "The current study found that patients with psoriasis had elevated serum IL-6 levels; however, levels in PsA patients were significantly higher." (PMID 39429270, 2024). "Anti-IL-6 therapies, effective for rheumatoid arthritis, are either ineffective for psoriasis or can induce new-onset psoriasis-like disease." (PMID 38793117, 2024).